CGAS (cyclic GMP-AMP synthase)
Diseases named in the same sentence as CGAS in open-access papers (continued):
Sharing a sentence is not in itself a finding about the gene and the disease.
viral infection (continued). "The cyclic GMP-AMP synthase (cGAS)-stimulator of interferon genes (STING) innate immune pathway has emerged as a critical driver of inflammation in a variety of settings, such as virus infection, cellular stress, tissue damage, and aging." (PMID 38503877, 2024). "Previous work suggested that inhibition of HDAC1 could trigger a cellular DNA damage response that resulted in the activation of cGAS; however, our data suggest that, at least in THP1 cells, viral infection is required for VPA to induce an IFN-I response." (PMID 38932169, 2024). "On the other hand, in HIV infection, TREX1 activity promotes a decrease in viral DNA below the threshold of immune activation, inhibiting the adequate activation of cGAS-STING and the production of IFN-I, which are essential for the control of viral infections." (PMID 38675842, 2024). "Since the cytosolic DNA sensor cGAS and its downstream STING-IRF signaling are essential machineries that mediate the IFN response during DNA damage and viral infection, we suspected that it may be involved in the ISGs production during necroptosis." (PMID 38926796, 2024). "Similar to the case of virus infection, pDCs may contribute to TLR9-mediated inflammation in autoimmune diseases, whereas cDCs mainly contribute to cGAS-mediated inflammation." (PMID 39254994, 2024). "However, deletion or silencing of cGAS or STING genes results in reduced production of type I IFN and enhanced viral infection, thus suggested that the host cGAS-STING signaling pathway plays an important role in limiting viral replication." (PMID 37600809, 2023). "Improper termination of cGAS-STING triggering in the presence of ARF1 R99C, e.g. after exogenous triggers like viral infection, might accelerate and aggravate disease progression." (PMID 37914730, 2023). "Thus, our findings deepen the understanding of porcine cGAS–STING pathway, which lays a foundation for effective antiviral therapeutics against porcine viral diseases." (PMID 37660925, 2023). "Since BAF inhibition increases type I interferon responses in a cGAS-dependent manner in multiple cell types, targeting BAF may be a viable approach for treating viral infections and malignancies." (PMID 36746947, 2023). "There is growing evidence that the cGAS–STING axis is one of the cellular pathways controlled by Ca2+ signaling, and the mechanism of this pathway regulating IFN-I response in microbial infection and viral diseases will be carefully studied in the future." (PMID 35859744, 2022). "Thus, signaling initiation by arginine methylation allows the characterization of direct methylation modifications of the cGAS protein and defines PRMT5 as a negative regulator of cGAS-mediated type I IFN production during viral infection." (PMID 36231006, 2022). "In addition, the mitochondria are involved in the cyclic GMP-AMP synthase (cGAS)-stimulator of interferon genes (STING) signaling pathway, activated by viral infection-induced host cell stress and dsDNA." (PMID 35795579, 2022). "Furthermore, both cGAS and IRF7 were upregulated in MIV and MgIV groups, suggesting that the type 1 interferon pathway was activated due to the transcription of cGAS and IRF7 triggered in response to viral infection." (PMID 36016774, 2022). "STING has been studied as a negative host factor for viral infections since it is a key component of the cGAS/STING/TBK1/IRF3 regulatory axis activating interferon pathway, and therefore as a target of viral immune evasion." (PMID 36455047, 2022). "IFN I (IFN-α and IFN-β) are at the heart of immune protection against viral infections, and the production of IFNα/β relies on the inherent recognition of cytoplasmic viral nucleic acids by PRR, including the DNA sensor cGAS, which signals through the adapter STING." (PMID 35812373, 2022).
viral infection (continued). "Another explanation could be an inflammatory condition induced by the cGAS-STING mechanism which is triggered by leakage of DNA from micronuclei into the cytoplasm and/or virus infection of the lungs." (PMID 35203522, 2022). "Thus, although our RLR or cGAS findings remain to be confirmed and extended with analyses of kinase-deficient Pim1, they tentatively suggest that targeting the kinase-independent interaction between Pim1 and the IRF3 signaling complex could help control viral infections." (PMID 36446848, 2022). "Stimulation of the cGAS-STING pathway by cytosolic viral DNA is a primordial mechanism of inducing autophagy flux to clear intracellular virus, forming the fundamental biology for cells to fending off viral infection." (PMID 35992877, 2022). "Thus, TRIM38/SENP2 controls both cGAS and STING protein stability in the early and late stages of viral infection to ensure the timely activation and inactivation to fine-tune the pathway responses." (PMID 35795661, 2022). "It will be important to identify RNAs that can bind and regulate the activity of cGAS in cells with or without virus infection." (PMID 34899698, 2021). "As cGAS and STING agonists are used for cancer and viral infection treatments, inhibition may promote these conditions." (PMID 34381828, 2021). "Thus, sensing of infection by BMD cells via cGAS and IRF7 is critical for resistance to a lethal viral disease in a natural host." (PMID 31877196, 2019). "Thus, the need for cGAS reinforces the importance of IFN-I in resistance to mousepox and the notion that cGAS can play a pivotal role in ISG induction after viral infection." (PMID 31877196, 2019). "At the upstream of the cGAS/STING signaling pathway, our previous study showed that an HSV-1 UL41 protein could degrade cGAS mRNA during viral infection." (PMID 31849849, 2019). "In addition, it has been shown that TLR9 contributes to the production of type I IFNs to systemic viral infections, while cytosolic nucleic acid sensors including cGAS, IFI16 (mouse: Ifi204), RIG-I, and MDA5 mediate local immune responses to viral infections." (PMID 29963044, 2018). "Transcription of cGas but not Zcchc3 was induced by viral infection or IFN-β stimulation in murine lung fibroblasts (MLFs)." (PMID 30135424, 2018). "It is thus curious that a recent study identified cGAS as playing important roles in inhibiting positive-sense single-stranded RNA (+ssRNA) viral infection, especially since RNA is not known to activate cGAS." (PMID 28620207, 2017). "In the absence of TREX1, viral infections including HIV1 infection cause accumulation of cytoplasmic DNA, which activates the cGAS-STING pathway leading to IFN-I production and eventually viral replication is inhibited." (PMID 29202128, 2017). "cGAS is able to bind cytosolic DNA during virus infection, which triggers cGAS to metabolize ATP and GTP into non-canonical cyclic dinucleotides (CDNs)." (PMID 27824940, 2016). "Notably, cGAS and STING transcripts and proteins were suppressed during WT but not mutant virus infections - even in STAT1-deficient cells - suggesting that Nsp15 contributes directly to their downregulation." (PMID 41880208, 2026). "While the cGAS/stimulator of IFN genes (cGAS/STING) signaling pathway has been well documented in mediating inflammatory responses during atherosclerosis progression, emerging evidence suggests potential crosstalk between Listerin and cGAS in viral infection contexts." (PMID 40526435, 2025). "Our results indicate that FPN1-maintained intracellular iron homeostasis is required for the manipulation of cGAS- and RLR-dependent downstream innate responses, revealing an additional immune escape mechanism and thereby providing promising therapeutic targets for the treatment of viral diseases." (PMID 40595467, 2025).
viral infection (continued). "Hence, the absence of a functional DNA sensor in cGAS−/− macrophages demonstrated some impacts not only on viral infection (IRF pathway) but also on LPS activation, possibly due to the presence of mitochondrial DNA in the cytosol after LPS induction." (PMID 40507879, 2025). "The innate immune system constitutes the primary defense against viral infections, employing pattern recognition receptors (PRRs), including Toll-like receptor 3 (TLR3), RIG-I-like receptors (RLRs), and cyclic GMP-AMP synthase (cGAS) to recognize viral elements and activate antiviral responses." (PMID 40264759, 2025). "Interestingly, it was recently shown that viral infection of RAW264.7 macrophages did not activate the cGAS-STING pathway, which is typically involved in cytosolic DNA sensing (26, –, 28)." (PMID 39846741, 2025). "The cGAS-STING pathway plays a role in the immune responses to various conditions, including respiratory system diseases, circulatory system diseases, digestive system diseases, nervous system diseases, viral infection, autoimmune diseases, tumorigenesis, and aging." (PMID 37600809, 2023). "To test whether E5 alone can trigger cGAS degradation without viral infection, we co-transfected a cGAS-expressing plasmid with an E5R-expressing plasmid or empty vector into HEK293T cells." (PMID 37217469, 2023). "Inappropriate activation of DNA sensors such as cyclic GMP-AMP synthase (cGAS) or Toll-like receptor (TLR 9) by self-DNA has been related to aberrant type I interferon signalling and ongoing inflammation in autoimmune and autoinflammatory disorders as well as in infectious (usually viral) diseases." (PMID 37256140, 2023). "However, cGAS lacking N-terminal domain strongly induces interferon responses to genotoxic stress but weaker responses to any bacterial or viral infection." (PMID 36139387, 2022). "Furthermore, we identified the cGAS/STING pathway, which was essentially induced by the leaked mitochondrial DNA, as a biologically relevant mechanism contributing to exaggerated inflammation in Terc−/− mice following viral infection." (PMID 35313074, 2022). "Both glutamylated and non-glutamylated cGAS species are observed at resting states, while during viral infection, expression of TTLL enzymes is downregulated, leading to increased populations of non-glutamylated cGAS for sensing viral DNA to initiate innate immunity." (PMID 35795661, 2022). "Additionally, STING can be activated independent of cGAS during virus infection, such as STING activation by cross-talk with RNA sensor RIG-I-MAVS complex, by virus-induced necroptosis, and by viral envelope mediated fusion process." (PMID 34578409, 2021). "In addition to viral infection, if cGAS cleavage by caspases occurs in physiological conditions or developmental stages, and if cGAS can be cleaved by non-caspase proteases remain interesting questions to answer." (PMID 33927185, 2021). "In addition to cGAS, AIM2, IFI16, and DAI are the cytosolic DNA receptors, activation of which could induce innate immune response to virus infections." (PMID 33664729, 2020). "The location of cGAS at the plasma membrane ensures the efficient discrimination between self- and non-self-DNA, as cGAS mutants defective in lipid binding induce potent IFN-I responses to genotoxic stress (self-DNA) but weaker responses to viral infection (non-self-DNA)." (PMID 33329537, 2020). "It is noteworthy that the cGAS/STING cascade has been viewed as an adjuvant target for vaccine applications.On the other hand, better understanding of the battle between the virus and the human host will most certainly improve the prevention and treatment of all viral diseases." (PMID 27705945, 2016).
viral infection (continued). "In conclusion, in this work, we found that STE could enhance cGAS-STING activation by facillating 2′-3′ cGAMP production, it shows obviously inhibitory effect on HBV replication, STE may be a promising potential drug for the therapy of chronic hepatitis B and also other viral infectious diseases." (PMID 41158134, 2025). "Interestingly, the cGAS-STING pathway, which mediates the development and prognosis of bacterial infection in mammalian cells in various ways, has been found to originate as a bacterial immune system that confers immunological protection against viral infection." (PMID 35095914, 2021). "Interestingly, nsPs 1–3 of CHIKV were also able to inhibit cGAS-STING mediated induction of a type-I IFN promotor, suggesting that multiple CHIKV proteins may work individually or in concert to antagonize cGAS-STING signaling during viral infection." (PMID 33057424, 2020). "Because early knowledge of the cGAS–STING pathway was not comprehensive initially, the studies conducted mostly focused on viral diseases, cancer, and autoimmune diseases." (PMID 34906241, 2021). "Notably, two recent studies showed that naked HBV DNA is sensed by the cGAS-STING pathway, whereas the packaged HBV genome appears not to be recognized during viral infection of human hepatocytes." (PMID 38675916, 2024).
autoimmune disease (159 papers, 2015 to 2026). A disorder resulting from loss of function or tissue destruction of an organ or multiple organs, arising from humoral or cellular immune responses of the individual to their own tissue constituents. "Uncontrolled activation of cGAS is one of the major causes of autoimmune diseases, manifesting as an overreaction of immune surveillance." (PMID 40595456, 2025). "Patients with functional mutations in Trex1 trigger autoimmune disorders by persistently stimulating the cGAS-STING signaling pathway due to the accumulation of their own DNA." (PMID 40028324, 2025). "Our results suggest cDCs as a therapeutic target of cGAS-inhibiting treatments for autoimmune diseases caused by cytosolic self-DNA accumulation." (PMID 39254994, 2024). "Abnormal activation of the cGAS pathway has been implicated in the pathogenesis of a multitude of autoimmune diseases, including systemic lupus erythematosus (SLE), Aicardi-Goutières syndrome (AGS), and IBD." (PMID 39050748, 2024). "Erroneous activation of cGAS has been implicated in a multitude of autoimmune diseases, including systemic lupus erythematous and Aicardi-Goutières Syndrome, positioning cGAS inhibition as a potentially significant therapeutic strategy." (PMID 39050748, 2024). "Aberrant activation of cGAS has been implicated in the development of autoimmune diseases such as AGS and SLE, and targeting cGAS is becoming a promising strategy for treatment of such diseases." (PMID 38166933, 2024). "The cGAS-STING pathway has been implicated in several monogenic autoimmune diseases, such as Aicardi–Goutières syndrome (AGS), where defects in AGS-causing genes lead to cytosolic nucleic acid accumulation and activation of cGAS-STING pathway." (PMID 38953896, 2024). "Due to its essential role in the pathogenesis, the cGAS–STING pathway has been suggested as a new therapeutic target for autoimmune diseases caused by cytosolic DNA accumulation." (PMID 39254994, 2024). "Our study suggests that inhibition of cGAS in one specific cell type, cDCs, will be sufficient to ameliorate autoimmune diseases caused by Trex1 deficiency." (PMID 39254994, 2024). "Malfunction of the cGAS pathway has been implicated in many autoimmune disorders, inflammatory diseases, and various cancers." (PMID 39050748, 2024). "Understanding the precise regulation of cGAS-STING pathway is important for developing therapeutics to treat several autoimmune diseases caused by self-DNA." (PMID 37120570, 2023). "It has been suggested that cGAS pathway activation is the key signaling for autoimmunity diseases caused by a TREX1 missense mutation." (PMID 37834184, 2023). "We map each TREX1 mutation associated with autoimmune disease and establish distinct categories of substitutions predicted to impact enzymatic function, protein stability, and interaction with cGAS-DNA liquid droplets." (PMID 35879334, 2022). "A recent publication has shown that POLB deficiency triggers cytosolic DNA mediated cGAS-STING signaling pathway activation in immune cells with autoimmune disease." (PMID 36624848, 2022). "Inappropriate activation of cGAS-STING immunity is directly linked to autoimmune disorders, including Aicardi-Goutières Syndrome, familial chilblains lupus, and retinal vasculopathy with cerebral leukodystrophy." (PMID 35879334, 2022). "Intense research in recent years has implicated that cGAS signaling plays a role in the initiation and pathogenesis of autoimmune diseases, cancers, Aicardi-Gourtières syndrome (AGS), skin cancer, acute pancreatitis, and sepsis." (PMID 34158863, 2021). "Some autoimmune diseases have been linked to mutations in genes that regulate the cGAS–STING pathway." (PMID 34906241, 2021). "The abnormal activation of cGAS in autoimmune diseases caused by incomplete self-DNA clearance has also been demonstrated in Trex1−/− and DNaseII−/− mice." (PMID 32180716, 2020).